RGR (retinal G protein coupled receptor)
Description:
Non-visual opsin that functions as a light-dependent facilitator of retinoid isomerization and trafficking in retinal pigment epithelium (RPE) and Mueller glia. Participates in a photic visual cycle by complementing the classical enzymatic RPE65/RDH pathway for chromophore regeneration (By similarity). Binds all-trans-retinal via a conserved Schiff-base lysine and, upon illumination, promotes photoisomerization of all-trans-retinal to 11-cis-retinal required for regeneration of visual pigments (By similarity). Also mediates light-dependent mobilization of stored all-trans-retinyl esters from lipid droplets to endoplasmic reticulum membranes, facilitating their processing into 11-cis-retinoids. May also modulate isomerohydrolase activity independent of light (By similarity). Although RGR is structurally a GPCR-family opsin, there is no consistent evidence that RGR activates G proteins or initiates a canonical second-messenger signaling cascade (Probable).
Synonyms: RP44
Tractability: Small molecule: it belongs to a druggable protein family. Antibody: its Gene Ontology location is reachable by antibodies, with high confidence; UniProt predicts a signal peptide or a membrane-spanning region; the Human Protein Atlas places it where antibodies can reach.
Gene: Protein-coding gene on chromosome 10 (84,230,666 to 84,259,960, forward strand). Ensembl gene ENSG00000148604.
Subcellular location: Membrane
Subcellular location (Human Protein Atlas): Vesicles; Cytosol; Plasma membrane
Pathways (Reactome):
Signal Transduction: G alpha (i) signalling events; Opsins
Gene Ontology:
Molecular function: protein binding; G protein-coupled photoreceptor activity; G protein-coupled receptor activity; retinal binding
Biological process: retinoid metabolic process; cellular response to light stimulus; G protein-coupled receptor signaling pathway; phototransduction; visual perception; detection of visible light
Cellular component: plasma membrane; membrane
Genetic constraint (gnomAD): Loss-of-function variants: 33 observed, 31.24 expected, observed/expected ratio (o/e) 1.06, 90% interval 0.8 to 1.41. The upper end of that interval is the gene's LOEUF score, 1.41, which puts it in group 5 of 6, group 1 being the genes least tolerant of losing a copy. Missense variants: 397 observed, 388.58 expected, observed/expected ratio (o/e) 1.02, 90% interval 0.94 to 1.11. Synonymous variants: 176 observed, 162.73 expected, observed/expected ratio (o/e) 1.08, 90% interval 0.96 to 1.23.
Homologues: Orthologues: chimpanzee RGR (99% identical), macaque RGR (98% identical), pig RGR (87% identical), rabbit RGR (83% identical), mouse Rgr (81% identical), rat Rgr (80% identical), dog RGR (80% identical), guinea pig RGR (71% identical), tropical clawed frog rgr (61% identical), zebrafish rgra (56% identical), zebrafish rgrb (38% identical), Caenorhabditis elegans npr-20 (16% identical). Paralogues in human: CCR4 (20% identical), CCR5 (19% identical), CCR9 (19% identical), CX3CR1 (19% identical), CXCR2 (19% identical), CCR3 (19% identical), CCR8 (19% identical), CXCR1 (19% identical), GALR2 (19% identical), CCR1 (18% identical), CXCR3 (18% identical), CCR2 (18% identical), and 11 more.
Diseases named in the same sentence as RGR in open-access papers:
RGR is named in the same sentence as 12 diseases in open-access papers, as found by Europe PMC text mining. Sharing a sentence is not in itself a finding about the gene and the disease. The quoted sentences say what the papers report.
retinitis pigmentosa (6 papers, 2015 to 2024). Retinitis pigmentosa (RP) is an inherited retinal dystrophy leading to progressive loss of the photoreceptors and retinal pigment epithelium and resulting in blindness usually after several decades. "Mutations in this RGR gene have been shown to be associated with retinitis pigmentosa and different forms of retinal diseases." (PMID 37351342, 2023). "Mutations in the human orthologous gene RGR are responsible for retinitis pigmentosa." (PMID 38556874, 2024). "This might be, because the human peropsin could not be linked to an eye disease, which contrasts with human RGR-opsin, which could be linked to retinitis pigmentosa." (PMID 35954284, 2022). "Strikingly, eight of the 67 exclusive candidates are associated with retinitis pigmentosa (human orthologues in parentheses): Gnat1 (GNAT1), Rom1a and Rom1b (ROM1), Kfharr-r2 (SAG, ARRESTIN, RP47), Rgra (RGR, RP44), Tbl2 (TBL2), Sec31b (SEC31B) and Glyr1 (GLYR1)." (PMID 34106226, 2021). "Novel mutations in the genes NR2E3 and RGR could be related to retinitis pigmentosa and affect the phenotype; still these were not likely to be the main causative genes." (PMID 26229699, 2015). "Interestingly, RGR, CNGA1, and RLBP1 play an important role in retinitis pigmentosa." (PMID 37179305, 2023).
retinal diseases (3 papers, 2010 to 2023). "We compared the significantly dysregulated genes identified in this screen (FDR <0.05) against genes linked to inherited retinal diseases and identified 5 genes: RGR, PRCD, CDH3, GM2A, and CYP2U1." (PMID 37115691, 2023). "known retinal disease genes (BEST1 [NM_004183], C1QTNF5 [NM_015645], CDH3 [NM_001793], LRAT [NM_004744], RDH5 [NM_002905], RDH11 [NM_016026], RGR [NM_002921], RLBP1 [NM_000326] and STRA6 [NM_022369])." (PMID 20479888, 2010).
vision disorder (2 papers, 2016 to 2023). Any impairment to the vision. "Among the novel GWAS-identified associations with AL, our study revealed potential candidate genes, including SLC25A12, BMP3, RGR, RBFOX1, and MYO5B, which have all been linked to visual function or eye development and have been implicated in vision disorders." (PMID 37351342, 2023). "Eight positively selected genes within the tarsier lineage were implicated in several diseases associated with eye development and visual disorders (BBS2, BFSP2, IDUA, IL1A, IMPG1, RGR, SRD5A3 and TMC8)." (PMID 27708261, 2016).
retinal dystrophies (1 paper, 2021). "In 1999, a homozygous Ser66Arg mutation and a heterozygous frameshift mutation in the RGR gene were associated with certain retinal dystrophies." (PMID 32493732, 2021). "Besides the physiological role of RGR identified in Rgr−/− mice, a mutation of RGR implicated in human retinal dystrophies also suggests that RGR plays a significant role in human vision." (PMID 32493732, 2021).
Skin Tumors (1 paper, 2022). "We further explored RGR expression in some skin tissues from pathological conditions, including benign proliferative diseases and skin tumor tissues." (PMID 35445026, 2022).
Usher syndrome type 2C (1 paper, 2012). "Several additional genes known to be involved in other forms of HRD were also located within these intervals, including the following: GPR98, underlying Usher syndrome type 2C; TOPORS, underlying adRP; and RGR, underlying arRP." (PMID 23233793, 2012).
tumor (4 papers, 2020 to 2025). "In vivo, RGR-mediated binding to PDGFRβ-expressing pericytes might contribute to the enhancement of tumor uptake of RGR-TRAIL." (PMID 35635308, 2022). "Accordingly, RGR-TRAIL induced greater apoptosis of tumor cells than TRAIL." (PMID 35635308, 2022). "Specifically, the level 3 classifier shows strong correlations among genes like KRT5, S100A7, KRT16, S100P, and LY6D, while the level 6 classifier exhibits similar patterns with GPR17, RGR, and NPPA, highlighting the complex interplay of genes in tumor subtype classification." (PMID 40802546, 2025). "In addition, five other genes, including TBPL1, USP28, NRG3, PPM1L, and RGR, were regulated by eRNAs expressed only in LGG tumor tissue; whereas SEMA4G was regulated by LGG-specific seRNAs." (PMID 35299740, 2022).
retinopathy (1 paper, 2018). "We describe the clinical features in two pedigrees with dominantly inherited retinopathy segregating the previously reported frameshifting mutation, c.836dupG (p.Ile280Asn*78) in the terminal exon of the RGR gene, and compare their haplotypes to that of the previously reported pedigree." (PMID 30347075, 2018).
RGR also shares sentences with these, for which no sentence is quoted: myopia (1 paper); pancreatic tumors (1); Photophobia (1); retinoschisis (1).